APC (APC regulator of Wnt signaling pathway)
Diseases named in the same sentence as APC in open-access papers (continued):
Sharing a sentence is not in itself a finding about the gene and the disease.
colon adenocarcinoma (18 papers, 2011 to 2026). "Next, we selected colon adenocarcinoma samples that harbour Wnt pathway activating mutations in the APC gene." (PMID 33292279, 2020). "Abnormal localization of β-catenin has been well documented in colonic adenocarcinomas with mutation in APC tumor suppressor gene." (PMID 23121893, 2012). "Germline APC mutations are responsible for familial adenomatous polyposis syndrome, and biallelic inactivation of APC occurs in the majority of sporadic colonic adenocarcinomas." (PMID 21403819, 2011). "In a second study, the same authors generated mice in which the expression of a constitutive PI3K and the loss of APC were induced simultaneously in colon cells: these mice developed many aggressive colon adenocarcinomas, thus indicating the capacity of PI3KCA mutations to synergize with APC loss." (PMID 29652830, 2018). "The expression of WNT1, APC was decreased in colon adenocarcinoma, and that of CTNNB1 was decreased in cholangiocarcinoma." (PMID 32764696, 2020). "We did observe a link between the presence of APC mutations and decreases in estimates of myeloid and CD8+ T cells in colon adenocarcinoma, but increases in NK estimates in kidney papillary carcinoma were observed." (PMID 28749946, 2017). "We treated LoVo, an APC/RAS mutant colon adenocarcinoma cell line, with VTD (10μM and 100μM)." (PMID 39502780, 2024). "Once the somatic mutations of all genes in colon adenocarcinoma were analyzed by COSMIC, the result showed that the majority of top 20 genes with somatic mutations are mRNA over expression (18/20) and CNA gain, except 2 genes (PCLO with high methylation and APC with high point mutation)." (PMID 29108255, 2017). "Other studies based on APC mutation, in combination with the inactivation of various members of the TGF-β family—such as TGFBR2, SMAD2, SMAD3 or SMAD4—resulted in the generation of invasive, but not metastatic, colon adenocarcinomas." (PMID 29652830, 2018).
hereditary cancer (18 papers, 2005 to 2025). Malignant neoplasms occurring in families at a rate greater than that expected by chance and caused by germline mutations in a specific gene. "Genetic testing confirmed a pathogenic variant in the APC gene: Next-generation sequencing MyRisk Hereditary Cancer identified a heterozygous APC c.3927_3931del (p.Glu1309Aspfs∗4) mutation in 2021." (PMID 41467151, 2025). "Next-generation sequencing analysis using a panel consisting of 53 hereditary cancer related genes revealed a maternally inherited APC (exon15cn_del) mutation and a paternally inherited BRAC1 (p.lle1824AspfsX3) mutation." (PMID 33842374, 2021). "De novo FAP with double germline mutations in APC and BRCA2, along with somatic ERBB2 mutations, is exceptionally rare among hereditary cancer cases." (PMID 39985003, 2025). "Understanding tissue specific differences in DNA repair pathways can shed light on the tissue specificity of familial cancer-predisposing mutations in genes such as BRCA1, BRCA2, or APC." (PMID 25033455, 2014). "The predominant form of hereditary cancer in the small and large intestine is known as Familial Associated Polyposis (FAP), which is mainly linked to defects in the Adenomatous Polyposis Coli (APC) gene." (PMID 26910063, 2016).
hereditary cancer syndrome (18 papers, 2016 to 2025). "Among them, APC, FAT4, CTNND1 and TLR2 seem to be the most promising genes because of their role in hereditary cancer syndromes, tumor suppression, cell adhesion and Helicobacter pylori recognition, respectively." (PMID 33525650, 2021).
lymphoma (16 papers, 2015 to 2022). A malignant (clonal) proliferation of B- lymphocytes or T- lymphocytes which involves the lymph nodes, bone marrow and/or extranodal sites. "Lwin and colleagues previously reported that adhesion of lymphoma cell lines to BMSCs causes the cells to enter a protected quiescent state, mediated through upregulation of Fzr, leading to degradation of APC/CFzr substrate Skp2 and an accumulation of p27." (PMID 27655696, 2016). "For instance, null mutation of FEN1 in mouse model harboring heterozygous mutation resulted in cancer predisposition including lymphoma and contributed to gastrointestinal cancer when combined with heterozygous mutation in adenomatous polyposis coli (APC) gene." (PMID 34809722, 2021). "Five genes, all with variants in two cases, were shown to be associated with lymphoma pathogenesis (ID3, PAX5, TBL1XR1, IGLL5 and APC) in previous studies." (PMID 35205758, 2022). "Preclinical findings showed that selective CDC20 and APC/CCDC20/APC/CCDH1 inhibitors, namely Apcin and proTAME, are effective against lymphoma and multiple myeloma cells, resulting in mitotic arrest and apoptosis and synergizing with clinically-relevant drugs." (PMID 35490245, 2022). "All cancers displayed moderate to strong cytoplasmic or membranous APC positivity in varying fractions of cells, although lymphomas were mainly APC negative." (PMID 35303016, 2022).
mutyh-associated polyposis (15 papers, 2008 to 2025). An autosomal recessive hereditary neoplastic syndrome caused by mutations in the MUTYH gene on chromosome 1p34.1. "The aim of the present study is to evaluate the prevalence of BE in a large cohort of patients with MUTYH-associated polyposis (MAP) and APC-associated adenomatous polyposis." (PMID 32088803, 2020). "APC is a widely utilized biomarker for the detection of adenomatous colon polyps, and the MUTYH mutation has the potential to diagnose a distinct type of rare colorectal adenoma (MUTYH-associated polyposis (MAP))." (PMID 40362431, 2025).
cervical cancer (14 papers, 2007 to 2024). A primary or metastatic malignant neoplasm involving the cervix. "Additionally, DNA methylation of APC in patients with human papillomavirus, puts them at high risk for developing cervical cancer." (PMID 38562145, 2024). "Furthermore, there are reports that APC promoter hypermethylation is linked with H. pylori-associated gastritis, cervical cancer, and esophageal adenocarcinoma." (PMID 22414247, 2011). "In vitro, hydralazine effectively inhibits adenomatous polyposis coli (APC) methylation and promotes APC re-expression, thus inhibiting cell growth in human cervical cancer cell lines." (PMID 37370809, 2023). "We confirmed that DAPK1, RARB, SLIT2, and WIF1 are aberrantly methylated in cervical cancer compared to normal tissue, whereas, APC, CDH1 and FHIT are less commonly methylated." (PMID 25826459, 2015). "The functional role of both genes has been well described in cancer, with the BCL2 homologue gene BAX playing a key role in tumour apoptosis as a proapoptotic gene and APC acting as a tumour suppressor gene, which is frequently inactivated in cervical cancer by hypermethylation." (PMID 17242701, 2007). "Specimens from 122 patients with cervical carcinomas (FIGO stage I-IV) were immunohistochemically (IHC) analyzed for β-catenin, APC and axin protein expression." (PMID 27577083, 2016). "Genes encoding several key regulators of the oncogenic Wnt/β-catenin pathway, such as CDH1 (E-cadherin), APC, and WIF1, are frequently silenced via dense methylation of their promoter regions in cervical cancer." (PMID 25826459, 2015). "Only two genes, the proapoptotic gene BAX and the tumour suppressor gene APC has been found to be consistently downregulated in lymph node metastases and recurrent cervical cancer." (PMID 26551527, 2015).
Stroke (14 papers, 2018 to 2025). Sudden impairment of blood flow to a part of the brain due to occlusion or rupture of an artery to the brain. "Overall, in preclinical studies, 3K3A-APC appears to have a reduced risk for bleeding and provides at least equivalent if not greater cytoprotection compared with recombinant wildtype APC in mouse models of stroke." (PMID 33790846, 2021). "Western blot analysis further verified that LIPUS promoted the expression level of APC in stroke mice." (PMID 40290135, 2025). "We previously detected high number of mature oligodendrocytes (APC+) in the corpus callosum (CC) and external capsule (EC) of cKO brains at 14 d post-stroke, which correlated with poststroke functional improvement." (PMID 35017668, 2022). "Cdh1 is the activator of APC/C and cyclin B1 is one substrate of APC/C–Cdh1, whose nuclear level is increased in affected neurons of stroke patients." (PMID 36438186, 2022). "IL-4 treatment increased the numbers of BrdU+APC+ cells or total BrdU+ cells after stroke in mice fed with the control diet." (PMID 31226122, 2019). "A promising approach for stroke therapy is based on recently discovered biological properties of APC, which is an endogenous plasma protease with multiple properties including antithrombotic action, cytoprotective propensity, and anti-inflammatory activity in the brain and spinal cord." (PMID 33790846, 2021). "Our work showed that the proliferation of APC+ cells after stroke was stimulated by R1 treatment." (PMID 34025400, 2021). "Importantly, IL-4 treatment still resulted in a significant enhancement of BrdU+APC+ oligodendrocyte regeneration in microglia/macrophage-depleted stroke mice." (PMID 31226122, 2019). "Moreover, the number of APC+-OLs in the CC of the IBZ and the number of PDGFRα+-OPCs in the cortex of the IBZ of ABCA−B/−B-T2DM stroke mice were also reduced (p < 0.05, n = 9/group)." (PMID 35572941, 2022). "In Alzheimer’s disease and stroke pathogenesis, APC/CCdh1 but not Cdc20, is expressed in post-mitotic mammalian neurons and the inactivation of Cdh1 by phosphorylation results in the accumulation of cyclin B1." (PMID 33218190, 2020). "In Alzheimer’s disease and stroke pathogenesis, APC/CCdh1, but not APC/CCdc20, is expressed in post-mitotic mammalian neurons, and the inactivation of Cdh1 by phosphorylation results in the accumulation of cyclin B1." (PMID 33260674, 2020). "Consistent with our previous results, the present data show that the numbers of APC+-OLs and PDGFRα+-OPCs as well as APC+/BrdU+-OLs and PDGFRα+/BrdU+-OPCs in the IBZ of ipsilateral brain in ABCA1-B/-B vehicle stroke mice significantly decreased compared with those in ABCA1fl/fl vehicle stroke mice." (PMID 32575457, 2020). "Significant depletion of microglia/macrophages did not change the number of BrdU+APC+ cells or total BrdU+ cells compared to microglia/macrophage-competent stroke mice." (PMID 31226122, 2019). "The lack of PPARγ expression in OPCs did not significantly impair oligodendrocyte replacement after stroke, as shown by comparable numbers of BrdU+APC+ cells in the ischemic brain from PPARγ-OPC KO mice and control mice at 35 d after MCAO." (PMID 31226122, 2019). "However, no APC signal was detected in glial fibrillary acidic protein (GFAP)+ astrocytes in the ischemic brain in our preclinical model of stroke." (PMID 31226122, 2019).
intestinal polyposis (13 papers, 2013 to 2025). "The second family comprised five full and paternal half sibling dogs with the APC variant (dogs O–S), and all dogs had histories of GI polyps." (PMID 37505844, 2023). "Genetic ablation or translational suppression of Myc rescues intestinal polyposis in APCMin/+ and conditional APC deficiency mouse models." (PMID 37138032, 2023). "Previously, the predilection sites for GI polyps were reported to be the stomach and large intestine in JRTs carrying the germline APC variant, and only one case had a history of a duodenal lesion among the 21 examined cases." (PMID 37505844, 2023). "FAP is a series of syndromes including gastrointestinal polyps, cancer, and extracolonic lesion caused by germline mutations of the APC gene." (PMID 35508985, 2022). "We previously reported that the predilection sites for GI polyps were the stomach and large intestine in JRTs with the germline APC variant, and there was only one case with a previous history of a solitary duodenal lesion among the 21 examined cases." (PMID 36288164, 2022). "Recently, we demonstrated that JRTs with GI polyps harbor identical germline variant in the APC gene, c.[462_463delinsTT] (OMIA ID: 001916–9615), in the heterozygous state." (PMID 33461531, 2021). "Recently, we demonstrated that JRTs with GI polyps harbor identical germline variant in the APC gene (c.[462_463delinsTT]) in the heterozygous state." (PMID 33461531, 2021). "Gardner syndrome, mainly manifested by multiple gastrointestinal polyps and universal lesions such as soft tissue tumor, ectopic teeth, osteoma, and retinal pigment epithelium, is a rare autosomal dominant genetic disorder caused by gene mutation in adenomatous polyposis coli (APC)." (PMID 33183289, 2020). "Alterations in gene expression have been previously reported in normal appearing mucosa of APC mutant mice after the development of intestinal polyposis." (PMID 26121046, 2015). "MA supplementation inhibits spontaneous intestinal polyposis without producing any sign of distress or toxicity in APC Min/+ mice." (PMID 23527181, 2013).
Obesity (13 papers, 2017 to 2025). Accumulation of substantial excess body fat. "Experimental evidence demonstrated that an obesity-causing mutation in the leptin receptor promoted the development of CRC in mice model with APC mutation, an important initiating event of subtype 1, whereas in MSI mice model, diet or weight change had no such effect." (PMID 33442661, 2021). "Interestingly, more co-occurrences between mutations were demonstrated in obesity group compared with normal group (APC and KRAS, PIK3CA and KRAS, etc.)Finally, we investigated the copy number variation (CNV) in two group." (PMID 33197880, 2020). "Importantly, the spectrum of post-APC driver gene mutations is influenced not only by which driver gene mutations are made redundant by obesity-induced cell signaling, but also by which neoplastic cells survive the tumor immunosurveillance, which is affected by the MHC-1 genotypic variation." (PMID 36046651, 2022). "BMI in our studied population showed a direct relationship with the transcriptional changes (downregulated) observed on selected genes (APC, ARNT, CYP2D6, LEPR, LRP12, and MYC), all of which are closely linked to the development of cancer or obesity." (PMID 35420343, 2022). "Moreover, accumulation of DNA mutations, such as APC, KRAS, NRAS, BRAF, or PIK3CA, makes obesity a multifactor phenomenon involved in CRC initiation and progression." (PMID 36235624, 2022). "CRC is related to environmental factors (e.g., smoking, diet, obesity, alcohol), immune system dysregulation, or genetics, such as mutations of microsatellite instability (MSI) genes MSH1, MLH1, and MSH6, adenomatous polyposis coli (APC), or nucleotide-binding oligomerization domain 2 (NOD2)." (PMID 40376304, 2025). "Furthermore, BC-specific mortality was higher in patients with obesity and WBCs with low LUMA levels and hypermethylation of the adenomatous polyposis coli (APC) and twist family bHLH transcription factor 1 (TWIST1) genes." (PMID 37512149, 2023). "Dietary fructose improves intestinal cell survival and nutrient absorption and studies have shown that daily oral administration of high-fructose corn syrup in adenomatous polyposis coli (APC) mutant mice led to a substantial increase in tumor size and tumor grade in the absence of obesity." (PMID 35681705, 2022).
rectal tumors (13 papers, 2005 to 2025). "Odds ratio testing revealed differential enrichment of APC co-mutations in colon versus rectal tumors." (PMID 40860720, 2025). "AXIN1 and APC co-mutations demonstrated location-specific enrichment between colon and rectal tumors." (PMID 40860720, 2025). "Data from colon and rectal tumors from The Cancer Genome Atlas (TCGA) shows that APC mutation rates differ among the 224 tumors sequenced by exome sequencing." (PMID 26884349, 2016). "Moreover, our results reveal that the CRP-286 SNP mutations tend to co-occur with mutant APC in colon and rectal tumors." (PMID 25025473, 2014). "Furthermore, our PCA performed with the TCGA cohort, based on expression data from different gene sets (all deregulated genes or subsets of genes from the Qiagen PCR Arrays) did not allow discriminating colon vs. rectal tumors or CRC samples according to APC or KRAS mutational status." (PMID 28962550, 2017).